FAP (fibroblast activation protein alpha)
Diseases named in the same sentence as FAP in open-access papers (continued):
Sharing a sentence is not in itself a finding about the gene and the disease.
Stroke (4 papers, 2013 to 2025). Sudden impairment of blood flow to a part of the brain due to occlusion or rupture of an artery to the brain. "In contrast to established cardiovascular risk factors, low FAP concentrations were the only parameter associated with stroke in the first week after the event, and were associated with a higher incidence of stroke or MI events in the long-term course." (PMID 36568546, 2022). "However, in our study we did not include patients with major neurological impairment and further studies will be necessary to evaluate a possible association between neurological impairment after stroke and FAP concentrations." (PMID 36568546, 2022). "Furthermore, lower FAP concentrations in stroke patients were associated with a cardio-cerebral event within 12-months after admission." (PMID 36568546, 2022). "Of note, FAP was the only parameter associated with the presence of stroke in our study." (PMID 36568546, 2022). "We argue that reduced FAP concentrations after stroke might be associated with the thrombo-embolic event: Correlation of circulating FAP with cleavage of alpha 2 antiplasmin has been demonstrated, indicating a possible role in fibrinolysis of acute thrombus burden." (PMID 36568546, 2022). "FAP encodes fibroblast activation protein alpha, which has been reported to be associated with inflammation and stroke; meanwhile, ANGPTL4 encodes angiopoietin-like 4, a protein expressed in vascular endothelial cells, which may have an influence on vascular atherosclerosis and ischemic stroke." (PMID 32796743, 2020). "A soluble form of FAP has been detected in blood, and reduced blood concentrations in acute MI, stroke or malignancy were observed." (PMID 40690098, 2025). "FAP concentration had a fair accuracy for identifying stroke in the receiver operating characteristic (ROC) analysis (AUC = 0.710, 95% CI: 0.577–0.843)." (PMID 36568546, 2022). "Stroke patients had a mean FAP concentration of 92 ± 24 ng/mL after the stroke event (median: 7 days; IQR 4–7 days), which was significantly lower compared with the control cohort (P < 0.001)." (PMID 36568546, 2022). "Of note, FAP concentration inversely correlated with stroke severity assessed by NIHSS (r = −0.318, p = 0.03)." (PMID 36568546, 2022). "We further analyzed the correlation of various markers of cardiovascular disease with FAP concentrations in control and stroke cohorts." (PMID 36568546, 2022). "Stroke severity as assessed by NIHSS inversely correlated with circulating FAP (r = −0.318, p = 0.04)." (PMID 36568546, 2022). "ROC showed a fair discriminative ability of FAP for the presence of stroke (AUC = 0.710, 95% CI 0.577–0.843)." (PMID 36568546, 2022). "It remains unclear whether FAP concentrations are already reduced before or just after stroke, indicating the need for further studies." (PMID 36568546, 2022). "Circulating FAP concentrations in stroke patients were 19% lower than in the control cohort." (PMID 36568546, 2022). "Importantly, while reduced FAP enzyme activity in the setting of stroke has been shown, to the best of our knowledge, our data show for the first time reduced FAP concentrations after stroke." (PMID 36568546, 2022). "Additionally, we show for the first time that FAP inversely correlates with stroke severity and that low FAP concentration (below 90 ng/mL) seem to be associated with higher risk of stroke or MI within 1 year after the acute event." (PMID 36568546, 2022). "Further studies are needed to evaluate the potential role of FAP as a novel biomarker in stroke and to establish whether low circulating FAP concentrations are a result of or can even serve as a predictor of future strokes or MI." (PMID 36568546, 2022). "Using a FAP concentration cutoff of >101 ng/ml, we calculated a sensitivity of 72%, specificity of 77%, positive predictive value of 81 % and negative predictive value of 68% to establish the diagnosis of stroke." (PMID 36568546, 2022).
Stroke (continued). "Previously published work showed that FAP concentration changes over time after stroke." (PMID 36568546, 2022). "For the first time, we established a ROC curve demonstrating the diagnostic value of FAP in discriminating between patients with and without stroke, yielding an AUC of 0.710." (PMID 36568546, 2022). "Using FAP concentrations, it might be possible to discriminate strokes from stroke mimics and functional outcomes." (PMID 36568546, 2022). "The reason for decreased FAP concentrations after stroke in our study remains unknown." (PMID 36568546, 2022). "In patients with stroke, blood samples were taken between the 3rd and 7th day after stroke-onset to avoid interactions within the acute phase, because it has already been shown that the expression of FAP is induced by macrophage-derived TNFα which is a mediator of post-stroke inflammation." (PMID 36568546, 2022). "Furthermore, we hypothesized that circulating FAP concentrations correlate with stroke severity and the occurrence of recurrent cardio-cerebrovascular events in the long-term course." (PMID 36568546, 2022). "To evaluate the ability of circulating FAP concentrations to discriminate patients with stroke from patients without stroke, we performed a ROC analysis." (PMID 36568546, 2022). "A FAP concentration of 101 ng/mL discriminated between presence and absence of stroke with a sensitivity of 72% and a specificity of 77%." (PMID 36568546, 2022). "FAP concentrations in stroke were not different in men (mean 91 ± 21 ng/mL) and in women (mean 88 ± 27 ng/mL) (p = 0.64)." (PMID 36568546, 2022). "Circulating FAP plasma concentrations were determined by ELISA in 47 patients with acute stroke and 22 control patients without stroke." (PMID 36568546, 2022). "Also, the parameter of diastolic function E/E' was not correlated with circulating FAP concentrations after stroke." (PMID 36568546, 2022). "We did not see different concentrations of FAP concerning stroke etiology." (PMID 36568546, 2022). "Neither inflammation, as evidenced by CRP-levels, nor overall stroke risk (CHA2DS2 VASc score), biomarkers of cardiovascular risk (NT-proBNP, CK) and echocardiographic parameters of atrial remodeling (septal PA TDI, LAVI/a) correlated with FAP concentration in our cohorts." (PMID 36568546, 2022). "Therefore, the present study investigated the hypothesis that circulating FAP concentration correlates with echocardiographic parameters representing left atrial remodeling and discriminates patients with ischemic stroke against those without stroke." (PMID 36568546, 2022).
acute myeloid leukemia (3 papers, 2022 to 2025). Acute myeloid leukemia (AML) is a group of neoplasms arising from precursor cells committed to the myeloid cell-line differentiation. "Similar findings in acute myeloid leukemia further underscore the importance of FAP as a potential indicator of adverse prognosis." (PMID 41373408, 2025). "Similarly, in acute myeloid leukemia (AML), overexpression of FAP has been linked to poor prognosis, with FAP’s role in activating β-catenin similarly protecting AML cells from apoptosis." (PMID 41373408, 2025).
brain cancer (3 papers, 2020 to 2025). A primary or metastatic malignant neoplasm affecting the brain. "Besides, FAP, overexpressed in several kinds of brain cancers, has been reported to be an excellent target for immunotherapy." (PMID 35874629, 2022). "FAP was also overexpressed in several paediatric brain cancers." (PMID 33082953, 2020).
colorectal adenocarcinoma (3 papers, 2015 to 2022). The most common type of colorectal carcinoma. "Pancreatic, breast, ovarian, and colorectal adenocarcinomas and their metastases have been demonstrated to be FAP-positive on PET/CT." (PMID 34168013, 2022). "Our analyses also showed that the activation of CAFs enhances the phenomenon of immunosuppression in colorectal adenocarcinomas, which is confirmed by the highly positive correlations between FAP-α and selected immune markers." (PMID 33625532, 2021).
desmoid tumor (3 papers, 2023 to 2025). A desmoid tumor (DT) is a benign, locally invasive soft tissue tumor associated with a high recurrence rate but with no metastatic potential. "FAP-associated desmoid tumor seems to be characterized by a more aggressive clinical course." (PMID 38254764, 2024). "All patients with desmoid tumors were included, both those with FAP‐related tumors and those with idiopathic tumors." (PMID 40847657, 2025). "Nevertheless, the overall treatment concept for FAP-associated desmoid tumors does not differ from that for non-FAP-associated desmoid tumors, although they are often treated with more aggressive systemic treatments." (PMID 38254764, 2024).
Duchenne muscular dystrophy (3 papers, 2025). Duchenne muscular dystrophy (DMD) is a neuromuscular disease characterized by rapidly progressive muscle weakness and wasting due to degeneration of skeletal, smooth and cardiac muscle. "However, under different pathological conditions, dysregulation of FAP activity occurs differently: In the muscles of patients with Duchenne muscular dystrophy (DMD) and long‐term radiation exposure, FAPs over‐differentiate into fibroblasts, causing fibrosis in skeletal muscle." (PMID 41305914, 2025).
esophageal adenocarcinoma (3 papers, 2015 to 2025). A malignant tumor with glandular differentiation arising predominantly from Barrett mucosa in the lower third of the esophagus. "In addition, stromal FAP expression was found in endothelial and lymphoid cells in esophageal adenocarcinoma." (PMID 25775399, 2015). "Esophageal adenocarcinoma (EAC) patients identified from the stromal molecular signature, including the CAFs marker FAP, had poorer outcomes, and gene ontology analysis identified a strong inflammatory component in disease progression." (PMID 40075643, 2025).
Fibroadenoma (3 papers, 2019 to 2025). A benign tumor of the breast characterized by the presence of stromal and epithelial elements. "The CAFs expressed higher αSMA and FAP than other benign fibroblasts, including fibroblasts from normal tissue, fibroadenoma and paracancer tissues." (PMID 31795965, 2019). "In contrast, benign tumors such as fibroadenomas demonstrated only moderate FAP+ fibroblast populations, suggesting that the high FAP expression in the former tumors reflects a phenotype that may be a valuable target for therapeutic intervention." (PMID 40542914, 2025).
infarction (3 papers, 2022 to 2025). A localised pathological necrosis of tissue resulting from obstruction of the blood supply usually by a thrombus, an embolus, or vascular torsion. "One of the new assumptions in tracking the post-infarction scar spreading is the expression of the FAP activation protein in activated fibroblasts in the process of wound healing following an ischemic event." (PMID 36613797, 2022).
liposarcoma (3 papers, 2022 to 2023). A usually painless malignant tumor that arises from adipose tissue. "FAP is overexpressed in cancer-associated fibroblasts (CAFs) in the stroma of more than 90% of epithelial carcinomas and many subtypes of STS (e.g., fibrosarcoma, malignant fibrous histiocytoma, and liposarcoma)." (PMID 35113192, 2022). "This may be caused by that the most cases included in the low-grade group were well-differentiated liposarcoma (3/5) and MSFT (1/5), which showed prominent expression of FAP on tumor cell surface." (PMID 35113192, 2022).
mammary adenocarcinoma (3 papers, 2015 to 2021). "HEK293 cells and MDA-MB-231 human mammary adenocarcinoma cells were transfected with FAPα cDNA to constitutively express FAPα, and subsequently xenografted into SCID mice." (PMID 25593080, 2015). "Indeed, FAP+ HO-1+ CD11b+ myeloid cells could be found in tissue sections of human mammary adenocarcinoma, indicating that this phenotype is conserved across murine and human tumours." (PMID 30054470, 2018).
Mast Cell Tumors (3 papers, 2017 to 2026). "Although polyclonal anti-FAP antibodies were previously utilized in canine mammary and mast cell tumor tissue samples, in our study, a monoclonal anti-FAP primary antibody was selected, as it showed a more specific staining pattern." (PMID 37727209, 2023). "An increase in FAP expression in canine mast cell tumour stroma by IHC has been recently demonstrated." (PMID 28531107, 2017).
metastasis (3 papers, 2015 to 2023). The spread or migration of cancer cells from one part of the body (where they first appeared) to another. "For global analysis, FAP overexpression in tumor tissue displayed significant associations with poor OS and tumor progression (OS: HR = 2.18, P = 0.004; tumor invasion: OR = 4.48, P = 0.007; and lymph node metastasis: OR = 3.80, P = 0.004)." (PMID 25775399, 2015).
myocardial ischemia (3 papers, 2021 to 2025). A disorder of cardiac function caused by insufficient blood flow to the muscle tissue of the heart. "Because spatial resolution of FAPI-PET is low, we aimed to analyze FAP-expression in a myocardial ischemia–reperfusion model in mice using immunohistochemistry, and complemented the results with autoradiography using 68 Ga-FAPI-46 distribution." (PMID 40029570, 2025). "We therefore aimed to characterize FAP expression in the AAR using a myocardial ischemia–reperfusion (MI/R) model in mice." (PMID 40029570, 2025).
neuroblastoma (3 papers, 2020 to 2023). Neuroblastoma (NB) is the most common solid, extracranial childhood tumor. "RO6874281 is a bispecific IL2 immunocytokine which targets cancer associated fibroblasts via binding to FAP and has shown potent anti-tumor activity in melanoma, neuroblastoma and colon carcinoma models." (PMID 32722460, 2020). "FAP targeted vaccines or FAP specific monoclonal antibodies have not been evaluated in neuroblastoma yet but can be used in future clinical trials." (PMID 32722460, 2020).
ovarian adenocarcinoma (3 papers, 2018 to 2025). An adenocarcinoma that arises from the ovary. "By contrast, FAP was low in expression in each subgroup that stratified ovarian adenocarcinoma we examined based on expression pattern of CAF- and EMT-related proteins." (PMID 29938002, 2018).
ovarian serous cystadenocarcinoma (3 papers, 2023 to 2024). A malignant serous cystic epithelial neoplasm arising from the ovary. "The pathological stages of specific tumor types, including BLCA, COAD, ESCA, Kidney chromophobe (KICH), KIRC, Kidney papillary cell carcinoma (KIRP), Ovarian serous cystadenocarcinoma (OV), and STAD, correlated significantly with FAP expression." (PMID 39055892, 2024).
polyneuropathy (3 papers, 2019 to 2024). A disease or disorder affecting more than one nerve. "We underscore the importance of including FAP-TTR among early differential diagnosis in patients with presumably idiopathic polyneuropathy." (PMID 38537102, 2024).
scleroderma (3 papers, 2020 to 2025). Scleroderma is a rare autoimmune connective tissue disorder characterized by abnormal hardening of the skin and, sometimes, other organs. "Adding to this, FB4 in scleroderma expressed higher levels of THY1 and fibroblast activation protein-α (FAP)." (PMID 37443817, 2023). "We demonstrated that both inflammation-driving subtypes, CCL19+ and SPARC+COL3A1+/FAP+THY+, are present in scleroderma, possibly promoting inflammation through chemotaxis and enhanced leucocyte infiltration." (PMID 37443817, 2023). "Further, FB4 in scleroderma expressed higher levels of THY1 and FAP." (PMID 37443817, 2023).
solitary fibrous tumor (3 papers, 2023 to 2025). Solitary fibrous tumor (SFT) represents a diverse group of ubiquitous rare spindle cell neoplasms that may be benign or malignant and that most frequently arises from the pleura and peritoneum and rarely from other sites such as head and neck, liver and skeletal muscle. "A striking example from the MASTER program involved identifying elevated expression of fibroblast-activating protein alpha (FAPα) in solitary fibrous tumors (SFTs), a rare sarcoma subtype that displayed the highest FAPα expression among all entities examined." (PMID 40427586, 2025).
aortic stenosis (2 papers, 2025). Aortic valve stenosis is a aortic valve disease caused by the incomplete opening of the aortic valve. "Recently, non-invasive imaging strategies using PET with radiolabeled FAP ligands have become available to characterize FAP expression in cardiovascular disease including acute ST-elevation myocardial infarction (STEMI) and severe aortic stenosis." (PMID 40029570, 2025).
astrocytoma (2 papers, 2021 to 2022). "Furthermore, they validated that FAP-positive cells existed in GBM and WHO III astrocytoma specimens by immunohistochemistry." (PMID 34068501, 2021).
bone metastasis (2 papers, 2015 to 2023). Transfer of a neoplasm from its primary site to bones. "For example, a low sensitivity for detecting bone metastasis was reported in one BC patient performing PET/CT for staging, probably due to low FAP expression in early osteogenic bone lesions." (PMID 36765866, 2023).
bone sarcoma (2 papers, 2014 to 2015). A sarcoma that arises from the bone. "The results of the present study revealed that bone sarcoma cell lines express FAP." (PMID 24520291, 2014).
brain injury (2 papers, 2022 to 2023). Acute and chronic (see also brain INJURIES, CHRONIC) injuries to the brain, including the cerebral hemispheres, CEREBELLUM, and brain STEM. "Other genetic modifications, such as fibrosis targeting anti-FAP CARs53, can also be performed to direct neutrophil nanocarriers to treat fatal regenerative diseases, including brain trauma and cardiac fibrosis." (PMID 37080958, 2023).
Chronic colitis (2 papers, 2019 to 2020). A chronic inflammatory disease of the large intestine (colon, cecum and rectum). "Markedly, FAP and PDPN were highly increased in the inflamed tissue of DSS-induced chronic colitis, which might be a hint for the pathogenesis of intestinal fibrosis and the underlying mechanism of berberine." (PMID 32332711, 2020). "In the tissue with chronic colitis, CCL-2 but not FAPα was also significantly high compared to the control." (PMID 31920487, 2019).
dilated cardiomyopathy (2 papers, 2024 to 2025). Cardiomyopathy which is characterized by dilation and contractile dysfunction of the left and right ventricles. "Prior studies have profiled pediatric dilated cardiomyopathy hearts with known genetic mutations and shown expansion of FAP+ activated fibroblasts in areas of active inflammation and fibrosis." (PMID 40502733, 2025).
ductal carcinoma (2 papers, 2021 to 2024). "In addition, FAP expression is observed in endothelial cells at the invasive front of ductal carcinoma, suggesting that FAP promotes capillary growth and invasion of the extracellular matrix." (PMID 34490078, 2021).
ductal carcinoma in situ (2 papers, 2014 to 2016). "Moreover, it is reported that FAP-α and calponin can serve as a novel marker for pathologically diagnosing the existence of microinvasion in ductal carcinoma in situ (DCIS)." (PMID 26716641, 2016). "In an attempt to improve diagnostic accuracy, markers used for immunohistochemistry have been studied, such as galectin-3, HBME-1 and CK-19 for diagnosis of benign and malignant thyroid lesions, and FAP-α and Calponin for diagnosing whether ductal carcinoma in situ has microinvasion." (PMID 24502396, 2014).
Ewing sarcoma (2 papers, 2009 to 2021). A small round cell tumor that lacks morphologic, immunohistochemical, and electron microscopic evidence of neuroectodermal differentiation. "In contrast, no tumour cells expressed FAP or DPP-IV in four Ewing’s sarcomas, two rhabdomyosarcomas, or one adamantinoma." (PMID 19817894, 2009). "In contrast, neither FAP nor DPP-IV is expressed in round or oval cells in Ewing’s sarcoma or rhabdomyosarcoma." (PMID 19817894, 2009).
follicular lymphoma (2 papers, 2025). Follicular lymphoma is a form of non-Hodgkin lymphoma characterized by a proliferation of B cells whose nodular structure of follicular architecture is preserved. "Other authors demonstrated the utility of FAP in follicular lymphoma." (PMID 40417720, 2025).